MUC1 (mucin 1, cell surface associated)
Diseases named in the same sentence as MUC1 in open-access papers (continued):
Sharing a sentence is not in itself a finding about the gene and the disease.
tumor (continued). "Instead, every tested MUC1 preparation, even non-glycosylated synthetic 9mer peptides, induced interferon gamma-producing CD4+ and CD8+ T-cells that recognized glycosylated variants including tumor-associated MUC1." (PMID 26788922, 2016). "The vaccine which is glycosylated with GalNAc at the unnatural amino acid, was capable of eliciting potent antibody responses recognizing both glycosylated and unglycosylated tumour-associated MUC1 peptides and native MUC1 antigen present on cancer cells." (PMID 29910919, 2016). "Failure to revaccinate post challenge was associated with down-regulated tumor MUC1 and MHC molecules." (PMID 26788922, 2016). "Here we have shown that the MUC1 gene generates a MUC1 mRNA that yields more than a single protein, resulting not only in the well-characterized tumor-associated MUC1-TM protein, but also a novel MUC1-ARF protein." (PMID 27768738, 2016). "We review here what is known about the role of specific cancer-associated glycans on MUC1 in protein-protein interactions and intracellular signaling in cancer cells and in their adhesion to each other and the tumor stroma." (PMID 27754373, 2016). "Truncated sugars on MUC1, such as T, Tn, and their sialylated forms, are associated with more advanced tumor stages and poor prognosis." (PMID 27754373, 2016). "We prepared whole cell digests from tumor-bearing mice that contained tumor cells as well as host antigen presenting cells, each of which possessed the MHC machinery to present tumor-associated MUC1." (PMID 26788922, 2016). "A similar approach has been used to increase the intensity of other tumour-associated antigens, i.e., mucin-1 (MUC-1) and prostate stem cell antigen (PSCA)." (PMID 27580852, 2016). "Tumor-associated MUC1 is characterized by altered glycosylation patterns, which enable differential targeting of tumor MUC1 for vaccine therapy." (PMID 27669306, 2016). "This time-dependent change in tumor susceptibility to lysis was corroborated using brachyury-specific or MUC1-specific T cells with PC9 and HCC4006 cells, respectively." (PMID 27685624, 2016). "In examining the ability of T-cells to recognize diversely glycosylated tumor-associated MUC1, it was important to consider the role that glycosylation played in antigen processing." (PMID 26788922, 2016). "A previous study reported an inverse association between the degree of MUC1 expression, and tumor grade and a recurrence rate." (PMID 27846863, 2016). "The novel vaccine is able to elicit a potent immune response in transgenic mice, recognizing both glycosylated and unglycosylated tumour-associated MUC1 derivatives and native MUC1 antigen present on cancer cells." (PMID 29910919, 2016). "The vaccine elicits robust antibody titers recognizing glycosylated and unglycosylated tumour-associated MUC1 derivatives and native MUC1 antigen present on cancer cells." (PMID 29910919, 2016). "Elevated levels of the hypoglycosylated MUC1 in tumors have been associated with increased invasiveness and metastasis of tumor cells." (PMID 25675408, 2015). "PankoMab-GEXTM, which is currently being evaluated for its therapeutic efficacy in a phase IIb clinical trial, is a glyco-optimized anti-MUC1 antibody specifically recognizing a tumour-associated MUC1 epitope (TA-MUC1)." (PMID 25986064, 2015). "We previously reported that CIN85, an 85 KDa protein known to be involved in tumor cell migration and metastasis through its interaction with Cbl, associates with MUC1 in tumor cells." (PMID 25675408, 2015). "A necessary feature of self-adjuvanting vaccines is that they target the immune system to particular, well-defined molecular epitopes such as tumor-associated glycoforms of the MUC1 VNTR." (PMID 26557640, 2015). "Mucin-1, one of the cell-surface-associated mucins encoded by the MUC1 gene, is expressed aberrantly in ~900,000 of the 1.4 million tumours diagnosed each year in the United States2." (PMID 25813863, 2015).
tumor (continued). "PankoMab-GEXTM is a novel, meanwhile fully humanized and glyco-optimized anti-MUC1 antibody selectively recognizing a glyco-epitope termed TA-MUC1 (Tumour-Associated MUC1)." (PMID 25986064, 2015). "In fact, MUC1 was listed by the National Cancer Institute pilot project as the second most promising target from a list of 75 potential tumor associated antigens (TAA)." (PMID 24416403, 2014). "Tumor-associated MUC-1, which is aberrantly glycosylated, is antigenically distinct from normal MUC-1 and it is associated with oncogenesis and resistance to chemotherapy." (PMID 25331657, 2014). "Taken together, the data suggests that tumor-associated MUC1 in KCM cells hinders myeloid maturation and drives the generation and maintenance of an immature, suppressive MDSC population partly via activation of the COX-pathway." (PMID 24605110, 2014). "MUC1 plays a role in inflammation and cancer progression and has recently been identified as the second most targetable tumor-associated antigen by the National Cancer Institute." (PMID 24605110, 2014). "Our current findings demonstrate for the first time, tumor-associated cell surface presence of MUC1 SP on several human tumor cell lines and primary tumors, with negligible presence on HMEC and white blood cells." (PMID 24416403, 2014). "Taken together, MUC-1 is important in tumor-progression and therefore a very interesting tumor-associated antigen." (PMID 24834066, 2014). "We report here a newly identified association of CIN85 with the hypoglycosylated tumor form of MUC1, which affects the functions of both molecules." (PMID 24072600, 2013). "MUC1 encodes a transmembrane glycoprotein that promotes the invasion of tumor cell and metastasis in tumorigenesis." (PMID 23405089, 2013). "Taken together, our data revealed that the two forms of tumor-associated, hypoglysylated Tn- and sialyl Tn-MUC1 are the optimal partner for CIN85." (PMID 24072600, 2013). "Here we show an important new association between CIN85 and MUC1 in tumor cells that involves both the cytoplasmic tail and the extracellular domain of MUC1." (PMID 24072600, 2013). "Elevated levels of MUC1 on the tumor have been associated with invasiveness and poor prognosis in colon, pancreas, breast and bladder cancer." (PMID 24072600, 2013). "Since then, MUC1 was considered to be a “tumor-associated antigen” which can be targeted in immunotherapy using monoclonal antibodies." (PMID 23509794, 2013). "We investigated what proteins in tumor cells associate with MUC1 and how those associations affect various tumor cell functions." (PMID 24072600, 2013). "MUC1 protein overexpression has been associated with cell adhesion inhibition as well as increased metastatic and invasive potential of tumor cells." (PMID 24073403, 2013). "It has been shown that the small tumor associated glycoepitope Tn on a MUC1 backbone is recognized by immune cells and elicits anti-tumor-antibodies." (PMID 24039759, 2013). "Using the anti-MUC1 antibody mPankoMab, which recognizes a special, tumor-associated MUC1 epitope, we previously observed a correlation between MUC1 and the expression of the ER receptor." (PMID 23890049, 2013). "Both MUC1 and miR-200c have been associated with tumor progression and epithelial to mesenchymal transition (EMT)." (PMID 24143167, 2013). "We identified CIN85, an adaptor protein involved in multiple cellular processes including signal transduction, cytoskeletal remodeling and cancer cell invasion, as one of several proteins that associate with MUC1 in tumor cells." (PMID 24072600, 2013). "Tumour-associated alterations of MUC1 such as hypoglycosylation, increased sialyation, and altered carbohydrate core-type expression are responsible for the antigenicity of MUC1 and hence its suitability as a target for immunotherapy." (PMID 23285151, 2012).
tumor (continued). "The possibility that tumor-associated MUC1 is aberrantly glycosylated has widely been discussed, and T cells can distinguish glycosylated from non-glycosylated peptides presented on MHC molecules." (PMID 23028615, 2012). "A number of synthetic glycopeptide vaccines with the MUC1 tumor associated glycopeptide epitope as target have recently been prepared." (PMID 23015828, 2012). "In the current study, we show that HSP70 associates with the C-terminal end of the MUC1 protein (MUC1-c) and transports it to the lysosome, thereby preventing lysosomal permeabilization and promoting cell survival in these tumor cells." (PMID 22912777, 2012). "MUC1 mAb clone SM3 was also used to detect the underglycosylated form of MUC1, which has been identified as a tumor associated form of MUC1." (PMID 22866263, 2012). "Mucins are membrane proteins largely investigated as tumor markers, and particularly MUC1 and MUC4 have been implicated in pancreatic carcinogenesis." (PMID 22458520, 2012). "Gd expression showed also a positive correlation with a tumour-associated epitope of MUC1 (TA-MUC1), which was stained by the PankoMabGEXTM antibody." (PMID 23036050, 2012). "MUC1 is also associated with invasion, controlling several cellular signaling pathways and tumor progression." (PMID 22912777, 2012). "The MUC1 cytoplasmic domain has been demonstrated to translocate to the nucleus, where it promotes the transcription of various genes linked to tumor cell invasion and metastasis." (PMID 22586492, 2012). "We observed that EGF induced nuclear localization of the MUC1 cytoplasmic domain leading to expression of genes linked to tumor cell invasion and metastasis including TWIST1, SNAI1 and SNAI2." (PMID 22586492, 2012). "MUC1 is a tumor-associated molecule frequently overexpressed in carcinomas and MUC3 is the major component of the glycocalyx of the small intestine." (PMID 22829946, 2012). "Once in the nucleus, MUC1 acts as a co-activator for the expression of genes linked to tumor cell invasion and metastasis including the EMT-promoting genes TWIST1, SNAI1 and SNAI2." (PMID 22586492, 2012). "MUC1 is one of the mucins that is associated with poor prognosis, malignant transformation of tumor cells, and resistance to genotoxic anti-cancer agents." (PMID 22912777, 2012). "Our results underline the possible prognostic potential of MUC1 in regard to tumour grade, FIGO stage and survival." (PMID 23241107, 2012). "The molecular characteristics of tumor-associated MUC1, its overexpression in virtually all adenocarcinomas and its functions as an oncoprotein make it a good target for the immunotherapy of cancer." (PMID 24212946, 2011). "Because MUC1 is over-expressed in many human carcinomas and cell lines where it is also associated with tumor progression, we investigated the relationship between intrinsic Δψm and endogenous MUC1 expression." (PMID 21966455, 2011). "MUC1 expression causes anchorage independent growth and tumor formation and is a useful marker for the prognosis of the patients with carcinoma." (PMID 24212784, 2011). "The target-directed immunotherapy with defined tumor antigens, such as melanoma-associated antigen 3 and mucin 1(MUC1), are suboptimal and strong adjuvant agents are needed." (PMID 21931708, 2011). "Expression of MUC1 was associated with tumor differentiation (OR: 4.71, 95% CI: 1.26, 17.66, P = 0.021)." (PMID 22027009, 2011). "The MUC1 glycoprotein has been implicated in multiple tumorigenic processes including tumour formation, proliferation, and survival." (PMID 21798038, 2011). "Using this approach, we expected to identify MUC1-CD-dependent genes intrinsically associated with an aggressive tumor behavior." (PMID 20459602, 2010). "MUC1 is another specific tumor-associated marker that has been already used for the detection of disseminating tumor cells." (PMID 19549321, 2009).
tumor (continued). "Tumour associated antigens on the surface of tumour cells, such as MUC1, are being used as specific antibody targets for immunotherapy of human malignancies." (PMID 19671134, 2009). "Overexpression of full-length MUC1 resulted in tumor formation in young mice (≤12 months); however, loss of either the cytoplasmic tail or the tandem repeat domain abrogated this oncogenic capacity." (PMID 21655373, 2008). "Tumor-associated alterations of MUC1 are characterized by hypoglycosylation, increased sialylation, and altered carbohydrate core-type expression." (PMID 19014671, 2008). "A significant association was seen between tumours with high MUC1 expression and a reduced DSS (mean DSS 54 months vs. 65 months; p = 0.038)." (PMID 17349047, 2007). "Binding analysis on recombinant but similarly glycosylated tumour-associated MUC1 would shed more light on this problem." (PMID 16265351, 2005). "This differential glycolsylation allows MUC1 to be exploited as a pan-carcinoma tumour-associated antigen with many B-cell and T-cell epitopes." (PMID 16265351, 2005). "Since glycosylation of MUC1 in cancer cells is distinct from mucin expressed in healthy tissue, tumour-associated mucin represents a valuable target for diagnostic and therapeutic approaches with monoclonal antibodies (mAbs)." (PMID 15150594, 2004). "MUC1 expression causes anchorage-independent growth and tumour formation, and is a useful marker for the prognosis of the patients with carcinoma." (PMID 15599383, 2004). "A panel of antibodies were raised against the tumour-associated form of the MUC1 antigen, particularly against the protein core motif." (PMID 12966437, 2003). "MUC1 mucin is aberrantly glycosylated and overexpressed in a number of epithelial malignancies and is therefore a promising tumour-associated antigen for target-directed immunotherapy of a panel of malignant diseases." (PMID 12966437, 2003). "However, soluble MUC1 is a known biomarker for prediction of prognosis and treatment efficacy as it was shown that MUC1 levels are associated with tumor burden." (PMID 40924700, 2025). "The biology of MUC1 is complex, however, early trials in cancer, where MUC1 is a well-studied tumour-associated antigen, suggest that monoclonal antibodies or inhibitors of MUC1 might represent a new therapeutic avenue for IPF." (PMID 39974050, 2025). "Bispecific CAR T-cells, engineered to simultaneously recognize HER2 and a second tumor-associated antigen, such as gp100 or MUC1, have shown the ability to eliminate solid tumors in preclinical models, including those located in the breast and brain of immunocompetent mice." (PMID 40940995, 2025). "Second-generation synthetic glycopeptide platforms such as MUC1-STn constructs linked to T-helper epitopes or formulated on nanoparticle carriers have elicited class-switched IgG and cytolytic T cell responses that recognize glycosylated MUC1 on tumor cells." (PMID 41228299, 2025). "In PDAC, MUC1 is overexpressed and hypo-glycosylated and is implicated in activation of several intracellular signaling pathways associated with oncogenesis, proliferation, and tumor dissemination." (PMID 40001578, 2025). "Tumor ablation achieves this organically by simultaneously releasing a vast array of canonical tumor-associated antigens (e.g., MUC1, CEA, HER2, NY-ESO-1) alongside a unique set of patient-specific neoantigens generated by the tumor’s individual mutational landscape." (PMID 41295487, 2025). "This difference is largely due to the fact that tumor-associated MUC1 is highly sialylated." (PMID 40443562, 2025). "MUC1 in normal cells is modified with highly complex O‐glycans; however, in cancer cells, glycan elongation stops, resulting in the formation of abnormally short glycans and an increase in tumor‐associated glycans, such as Tn, T, STn, and ST antigens." (PMID 40844495, 2025).
tumor (continued). "To date, MUC1 has shown great potential as a diagnostic marker and tumor treatment in NSCLC with KRAS mutation but its role in PDAC and CRC is almost unknown." (PMID 40013338, 2025). "In principle, these antibodies may target tumor-associated antigens such as MUC1 or mesothelin, patient-specific neoantigens, or even self-antigens, as reported in other cancers." (PMID 41008793, 2025). "And the appearance of aberrant glycosylation leads to the formation of new glycan epitopes and the exposure of peptide chain epitopes, which cause the tumor cell-specific antigenic epitope formation, making MUC1 a tumor-associated antigen (TAA) recognized by the immune system." (PMID 39491020, 2024). "Particularly, MUC1, whose aberrant expression is linked to tumor proliferation and LNM." (PMID 38181281, 2024). "Indeed, previous studies have demonstrated that MUC1 expression is associated with unfavorable outcomes, given its major oncogenic role in tumor progression, chemoresistance, and the establishment of an immunosuppressive microenvironment." (PMID 38254882, 2024). "Previous studies have shown that the high expression of MUC1 in tumor tissues is closely associated with the poor prognosis of cancer patients, and the high MUC1 expression can promote tumor progression by affecting the intrinsic and extrinsic apoptotic pathways." (PMID 37666495, 2024). "Tumor-related MUC1 exhibits certain features, such as loss of apical localization and aberrant glycosylation that might cause the formation of tumor-related antigen epitopes." (PMID 38540735, 2024). "The conjugate MUC1-β-TF with bacteriophage Qβ carrier triggered the production of high levels of IgG that could recognize diverse glycoforms of the tumor-associated MUC1 antigen." (PMID 39591192, 2024). "Although numerous antigens have been identified as potential targets (e.g., Trop2, GD2, ROR1, MUC1, EpCAM), the ideal target should represent the most relevant obstacle, thereby minimizing on-target/off-tumor toxicities and reducing tumor escape via antigen loss and intrinsic heterogeneity." (PMID 39062758, 2024). "Acs reported that the peripheral MUC1/EMA expression in IMPC tumor cell clusters might be associated with tumor progression and lymphatic metastasis." (PMID 38181281, 2024). "However, MUC1 also causes radio- and chemoresistance during cancer treatment and promotes tumor invasion and migration." (PMID 38540735, 2024). "MUC1 also binds to Siglec‐9 on the surface of bone marrow cells such as tumor‐associated macrophages (TAMs) and DCs, promotes the secretion of factors related to tumor progression, and activates the MEK–ERK signaling axis to regulate the phenotype of TAMs in the TME to promote tumor progression." (PMID 37666495, 2024). "Tumor-related MUC1 exhibits certain features, such as loss of apical localization toward a peripheral one and aberrant glycosylation that might cause the creation of tumor-related antigen epitopes." (PMID 38540735, 2024). "MUC1 dysregulation has been linked to tumor development, metastasis, and poor clinical outcomes." (PMID 38910324, 2024). "Based on the aspects such as therapeutic function, immunogenicity, specificity, and expression level, the NCI Translational Research Working Group prioritized MUC1 as the second‐best potential target out of 75 tumor‐associated antigens for the development of cancer vaccines." (PMID 38344400, 2024). "The retrograde trafficking of EGFR towards the nucleus was a tumor-specific event that could be driven by the association with MUC1 or a loss of polarity, and these data prompted us to evaluate targeting this pathway therapeutically." (PMID 36253541, 2023). "Thus, this review will explore the different generations of CAR-T cells, how they are genetically engineered, and their potential role in immunotherapy; targeting ErbB and MUC1, tumour-associated antigens which are highly expressed by HNSCCs." (PMID 39935547, 2023).